SLC3A1 (solute carrier family 3 member 1)
Diseases named in the same sentence as SLC3A1 in open-access papers (continued):
Sharing a sentence is not in itself a finding about the gene and the disease.
cystinuria (continued). "Two genes, SLC3A1 and SLC7A9, coding respectively for rBAT and b0,+AT, account for the genetic basis of cystinuria." (PMID 28717662, 2017). "To test the mechanism in vivo, we treated female and male SLC3A1 KO mice with a NAD+ precursor, NMN, for two weeks, to determine if it could rescue the sex differences of cystinuria." (PMID 40110490, 2025). "Cystinuria genes were identified 5 times (SLC7A9 and SLC3A1) in 5 patients (5%)." (PMID 40126616, 2025). "With the exclusion of SLC7A13/AGT1 as the third cystinuria gene accounting for the SLC3A1 and SLC7A9 mutation negative cases, it becomes obvious that other genetic factors should be responsible for the cystinuria phenotype in nearly 15% of patients." (PMID 30342472, 2018). "The absence of the CaM KMT activity can thus contribute to the mental retardation and mitochondrial defect observed in the 2p21 deletion patients but not in the hypotonia cystinuria patients with the absence of only the SLC3A1, PREPL alone." (PMID 23285036, 2012). "In this study, we reviewed the SLC3A1 and SLC7A9 variants identified from cystinuria patients of our institute, which revealed novel variants not reported to date as well as reclassified a previously reported variant of uncertain significance as a likely pathogenic variant." (PMID 37439839, 2023). "However, with the exception of populations with founder mutations, the detection rate for mutations in the SLC3A1 and SLC7A9 genes never reaches 100%, and genetic variants in both genes account for 80–85% in the cystinuria population." (PMID 30342472, 2018). "Mutations in non-explored regions of SLC3A1 and SLC7A9 could be responsible for the cystinuria phenotype in these unidentified cases." (PMID 26359869, 2015). "However, linkage analyses in cystinuria families did not indicate the existence of more than two cystinuria loci, 2p21 (SLC3A1) and 19q13 (SLC7A9), therefore the localisation of further genes encoding amino acid transporter subunits within this region was conceivable." (PMID 22480232, 2012). "Considering the observation that in many studies the detection rates for mutations in SLC3A1 or SLC7A9 do no reach 100% and due to the complex nature of renal amino acid transport, the role of further genes and modifying factors in the etiology of cystinuria have been postulated." (PMID 22480232, 2012).
breast carcinoma (18 papers, 2018 to 2026). "rBAT is encoded by SLC3A1 and is overexpressed in breast cancer cells promoting tumorigenesis via rBAT mediated Cys uptake." (PMID 33401748, 2021). "SLC3A1 (also known as rBAT) is a Na+-independent transporter of cystine and neutral and dibasic amino acids, which has been reported to be associated with breast cancer tumorigenesis." (PMID 29562706, 2018). "Although at lower levels, SLC3A1 is also upregulated in PCa (p-value < 0.001, GENT2 T-test), with overexpression in breast cancer associated with tumourigenesis." (PMID 40064858, 2025). "The chemotherapy drug sulfasalazine can induce ferroptosis in breast cancer cells by specifically inhibiting the function of SLC3A1, and the use of this function in treating breast cancer is in Phase II clinical trials." (PMID 39664391, 2024). "Although at lower levels, SLC3A1 is also upregulated in PCa (P < 0.001, GENT2 T-test), with overexpression in breast cancer associated with tumourigenesis." (PMID 38947031, 2024). "SLC3A1 was also found to be highly expressed in breast cancer tissues compared to peritumoral tissues and was correlated with breast cancer histological grade and progression." (PMID 39026605, 2024). "SLC3A1 expression has been shown to be upregulated in breast cancer cell lines, increased cysteine uptake, and promoted tumorigenesis of breast cancer cells." (PMID 39026605, 2024). "In breast cancer, upregualted SLC3A1 reduced ROS content and activated Akt signaling pathway, which resulted in promoted tumor growth." (PMID 37268653, 2023). "Overexpression of SLC3A1 enhances tumor progression in breast cancer cells, while blocking SLC3A1 with specific siRNA or SLC3A1-specific inhibitor sulfasaliazine inhibits tumor growth." (PMID 36505465, 2022). "SLC3A1, the cysteine carrier, has been reported to promote breast cancer tumorigenesis via AKT signaling." (PMID 36620592, 2022). "Sulfasalazine is an SLC3A1 inhibitor that suppresses the breast cancer growth response to antioxidant N-acetylcysteine." (PMID 29562706, 2018). "Intriguingly, the potential role of SLC3A1 in cancer was identified in breast cancer." (PMID 39026605, 2024). ",15,37, 38, 39 SLC3A1, an auxiliary subunit of the rBAT–b (0,+)AT1 (SLC7A9) transporter system, is linked to the capacity of breast cancer cells to maintain their redox state by promoting the accumulation of reduced GSH, thereby decreasing lipid peroxide levels and maintaining cell survival." (PMID 39437660, 2024). "Index patient 2 presented three likely pathogenic variants SLC3A1 c.1400T > C, MAT1A c.826dupG, and PTGIS c.824G > A. Breast cancer cells have elevated expression of SLC3A1, which accelerates cysteine uptake and accumulates reduced glutathione and decreases reactive oxygen species in tumor cells." (PMID 37628631, 2023). "SLC3A1 was reported to be involved in the occurrence of breast cancer." (PMID 31140607, 2019). "Intriguingly, SLC3A1 increased the cysteine uptake and hence GSH synthesis, and reduced reactive oxygen species in breast cancer cells." (PMID 39026605, 2024). "SLC3A1 increases GSH expression and activates AKT, promoting breast cancer tumorigenesis." (PMID 35892844, 2022).
kidney stones (10 papers, 2012 to 2025). "All of our patients who inherited two recessive SLC3A1 mutations from their heterozygous asymptomatic parents and had nephrolithiasis in the first decade of life." (PMID 33262960, 2020). "Cystineuria is a rare hereditary disease associated with kidney stones, which is primarily caused by mutations in two protein subunits (rBAT and b0,+AT) encoded by SLC3A1 and SLC7A9." (PMID 33109206, 2020). "The monoallelic VUS in the SLC3A1 gene was identified in a 39-year-old woman with bilateral severe medullary nephrocalcinosis, calcium, and phosphate containing kidney stones and CKD stage 2." (PMID 40428323, 2025). "12% of double mutants (3 of 24 Slc7a9-/-Slc3a1-/- mice) showed renal calculi that filled the cavity of the renal papilla acquiring a staghorn shape, which collapsed the kidney and led to renal failure." (PMID 26359869, 2015). "Indeed, more than 95% of all carriers of two SLC3A1 or SLC7A9 mutations (genotypes AA, BB, AB) will develop kidney stones in their live but the age of kidney stone formation is difficult to predict and shows a broad intrafamilial variability." (PMID 22480232, 2012).
hypotonia-cystinuria syndrome (7 papers, 2009 to 2020). A rare syndrome including neonatal and infantile hypotonia and failure to thrive, cystinuria type 1 and nephrolithiasis, growth retardation due to growth hormone deficiency, and minor facial dysmorphism. "The second disorder is atypical hypotonia-cystinuria syndrome (HCS) caused by a smaller deletion of 77.4 kb on the 2p21 chromosome that encompasses SLC3A1, PREPL and similarly to the first report the first exon of CaM KMT." (PMID 23285036, 2012). "For instance, patients with a relative mild HCS (hypotonia-cystinuria syndrome) are missing both alleles of SLC3A1 (solute carrier family 3, member 1) and PREPL on chromosome 2p21." (PMID 19575798, 2009). "Hypotonia-Cystinuria syndrome (HCS) is a rare disease, caused by a mutation in two contiguous genes (SLC3A1 and PREPL) localized on chromosome 2p21, and it is characterized by both renal involvement with cystine stones and nervous involvement with hypotonia." (PMID 31024870, 2019). "In addition to isolated cystinuria, patients suffering from the hypotonia-cystinuria syndrome have been reported carrying deletions including at least the SLC3A1 and the PREPL genes in 2p21." (PMID 22480232, 2012). "Hypotonia-cystinuria syndrome (HCS) associated with combined mutations in PREPL and SLC3A1 (a contiguous gene to PREPL on chromosome 2p21) comprises type A cystinuria, growth hormone deficiency, and fatigable muscle weakness." (PMID 29874875, 2018). "Larger deletions affecting SLC3A1 might result in the so-called hypotonia-cystinuria syndrome (HCS; OMIM 606407)." (PMID 22480232, 2012).
Aminoaciduria (4 papers, 2015 to 2025). An increased concentration of an amino acid in the urine. "The review highlighted 9 genes associated with aminoacidurias, including SLC3A1 (rBAT), SLC7A9 (bo,+AT), SLC6A19 (BoAT1), SLC7A7 (y+LAT1), SLC7A6 (y+LAT2), SLC36A2 (PAT-2), SLC6A20 (SIT-1), SLC6A18 (BoAT3), and SLC1A1 (EAAT3)." (PMID 41142409, 2025).
Hypotonia (4 papers, 2012 to 2022). Hypotonia is an abnormally low muscle tone (the amount of tension or resistance to movement in a muscle). "The raw WES data were evaluated for copy number variants in the SLC3A1 and PREPL genes and revealed a homozygous deletion in this region that could be confirmed by Sanger sequencing and led to the diagnosis of hypotonia-cystinuria syndrome." (PMID 25735936, 2015).
cystinuria type A (3 papers, 2014 to 2019). "We phenotypically characterized a mouse model of cystinuria type A resultant from knockout of Slc3a1." (PMID 31221135, 2019).
urolithiasis (3 papers, 2021 to 2023). Stone(s) within the urinary tract. "Some undetected alleles or loci may underlie the heterozygous carriers of SLC3A1 mutations that cause urolithiasis." (PMID 37144129, 2023).
kidney cancer (2 papers, 2022 to 2025). Primary or metastatic malignant neoplasm involving the kidney. "The results revealed that the basal expression profiles of MAP7, SLC16A12, and SLC3A1 were high in kidney cancer cells." (PMID 36620592, 2022).
lung carcinoma (2 papers, 2022 to 2025). "Intriguingly, based on our single-cell RNA-seq data, we classified TME cells in lung cancer into seven main cell types and discovered that FDXL, DLD, SLC3A1, and PDHA1 were differentially expressed in macrophages." (PMID 36263125, 2022).
chronic kidney disease (1 paper, 2025). Impairment of the renal function secondary to chronic kidney damage persisting for three or more months. "In contrast to the role of androgens in accelerating chronic kidney disease, we did not observe a significant difference between normal Slc3a1 KO males and orchiectomized Slc3a1 KO males." (PMID 40110490, 2025).
clear cell renal carcinoma (1 paper, 2023). A malignant epithelial neoplasm of the kidney characterized by the presence of lipid-containing clear cells within a vascular network. "The highest scoring gene not previously associated with cancer was SLC3A1, the expression of which was found to be strongly associated with metastatic disease in clear cell renal cancer." (PMID 37669321, 2023).
cystine urolithiasis (1 paper, 2020). Urolithiasis in which the composition of the stones is predominantly cystine. "Rare variants on SLC3A1 AND SLC7A9 detected in 13 families with cystine urolithiasis." (PMID 32133030, 2020).
ovarian carcinoma (1 paper, 2022). A malignant neoplasm originating from the surface ovarian epithelium. "SLC3A1 may also be associated with tumorigenesis or recurrence in ovarian cancer." (PMID 35892844, 2022). "We found that PEG10 and SLC3A1 are the marker genes of cancer cells in the earliest stage or cancer stem-like cells in ovarian cancer; C0, one of the two malignant tumor clusters, includes these cancer stem-like cells." (PMID 35892844, 2022). "In the present study, we identified PEG10 and SLC3A1 as the marker genes of ovarian cancer-initiating cells." (PMID 35892844, 2022). "Therefore, PEG10 and SLC3A1 could be used to narrow down cancer stem cells in ovarian cancer." (PMID 35892844, 2022). "In particular, since SLC3A1 exists in plasma membrane and exhibits low expression in normal ovarian cancer, it may be helpful as a new cell surface marker of ovarian cancer stem cells." (PMID 35892844, 2022).
pancreatic cancer (1 paper, 2021). "Five mRNAs were shared between the two datasets, with SLC3A1 and IAPP down-regulated whereas CXCL14, ANLN, and TPRS1 up-regulated in pancreatic cancer." (PMID 33925948, 2021).
periodontitis (1 paper, 2023). An acute or chronic inflammatory process that affects the tissues that surround and support the teeth. "However, the expression of SLC3A1 was significantly decreased in periodontitis group." (PMID 37215133, 2023). "Then we used IHC staining to test the three most significant different genes from qPCR analysis(NLRP3, DLST and SLC3A1), evidence from IHC results showed that NLRP3 and DLST were significantly increased in the 10 periodontitis tissues than control samples." (PMID 37215133, 2023).
renal colic (1 paper, 2025). A severe intermittent and spasmodic pain in the lower back radiating to the groin, scrotum, and labia which is most commonly caused by a kidney stone (RENAL CALCULUS) passing through the URETER or by other urinary track blockage. "A 32-year-old female heterozygous for the SLC3A1 variant c.1400T>C, p.Met437Thr presented with multiple bilateral stones, many episodes of renal colic, and multiple urological interventions." (PMID 40428323, 2025).
renal fibrosis (1 paper, 2022). A final common manifestation of a wide variety of chronic kidney diseases characterized by glomerulosclerosis and tubulointerstitial fibrosis. "The worsening renal fibrosis is associated with a reduction of the PT marker Slc3a1, whereas NKCC2 is increased, likely to compensate for the diminished NCC function." (PMID 35468900, 2022).
tumor (16 papers, 2015 to 2024). "Using a small cohort of patient derived tumor spheroids, we showed an inherently higher autophagy as well as higher expression and membranous localization of SLC3A1 in these platinum sensitive relapse patients." (PMID 39123206, 2024). "The protein levels of HPA demonstrated that MAP7 and SLC27A2 levels were lower, and SLC3A1 levels were higher, in tumor tissues than in normal samples, in accordance with the results of the TCGA-KIRC and RT-PCR." (PMID 36620592, 2022). "Expression of SLC3A1 enhanced tumorigenesis in tumor cells, whereas inhibition of SLC3A1 suppressed tumor growth." (PMID 31231376, 2019). "Specifically, one group consisted of primary and stem-like tumor cells, and SLC3A1 and PEG10 served as genetic indicators for tumor-initiating cells." (PMID 38022625, 2023). "The result showed that the gene expression of SLC3A1 and GLUL were highly expressed in Macro_APOE/CTSZ compared with other cell types in CRC and LC, and were upregulated in macrophage derived from tumor than normal tissues in CRC." (PMID 36587392, 2023). "The common prognostic genes between AS event and genes included KRT222, LENG8, APOB, SLC3A1, SCD5, AQP1, and ADRA1A, which played roles in tumor biology." (PMID 31140607, 2019).
cancer (15 papers, 2015 to 2025). A tumor composed of atypical neoplastic, often pleomorphic cells that invade other tissues. "SLC3A1 was associated with cysteine uptake, increased level of reductive glutathione and protected cancer cells from reactive oxygen species." (PMID 32647070, 2020). "Notably, both SLC7A11 and SLC3A1 demonstrated marked differential expression across almost all cancer types." (PMID 38397869, 2024). "Finally, RT-PCR showed that MAP7, SLC16A12, and SLC27A2 decreased, while SLC3A1 increased, in cancer cells." (PMID 36620592, 2022). "SLC3A1 can be considered as a cell surface marker of cancer-initiating cells." (PMID 35892844, 2022). "Additionally, as a co-enzyme with SLC3A1 coordinates group of five transportation/exchange reactions of L-Cystine, L-Alanine and L-Ornithine, that were also detected as differentiating the cancer data." (PMID 33287006, 2020). "C0 included cancer-initiating cells expressing PEG10 and SLC3A1, while C4, specifically expressing CA125, appeared later and was derived from the oldest cells." (PMID 35892844, 2022). "SLC3A1 and PEG10 were identified as the marker genes of cancer-initiating cells." (PMID 35892844, 2022). "While xCT has gathered much interest in cancer metabolism, cystine can be taken up by the cells through the activity of other transporters, including solute carrier family 3 member 1 (rBAT, SLC3A1), which does not require the simultaneous exchange with glutamate." (PMID 40278372, 2025). "Furthermore, although xCT has been a focal point in cancer metabolism studies, cystine can also be transported into cells via alternative transporters, such as solute carrier family 3 member 1 (rBAT, SLC3 A1), which does not require glutamate export." (PMID 40278356, 2025). "Additionally, we identified SLC3A1 and PEG10 as the marker genes of the earliest cancer cells." (PMID 35892844, 2022). "Furthermore, we identified SLC3A1 and PEG10 as the marker genes of cancer-initiating cells." (PMID 35892844, 2022). "Similarly to other markers of cancer stem cells, the mechanism by which cancer stem-like cells express PEG10 and SLC3A1 remains unknown." (PMID 35892844, 2022).
infection (2 papers, 2016 to 2022). The state of being infected such as from the introduction of a foreign agent such as serum, vaccine, antigenic substance or organism. "No significant changes in the levels of expression of podocyte marker genes (WT1, PODXL, NPHS1, NPHS2, and MAFB) or for tubular marker genes (SLC3A1 and SLC16A1) were found after infection comparing WT and ACE2 KO kidney organoids." (PMID 35561674, 2022). "However, the expression of Pkd2, Pkhd1, Kif12, Cadherin16 and Socs3, which are known as HNF-1β target genes, did not change (data not shown), and only a few genes, including NR1H4, MITF, SLC3A1, and SLCO4C1, were significantly upregulated 9 h after Ad-HNF1B infection." (PMID 27196561, 2016).
mitochondrial disease (2 papers, 2020 to 2021). "In contrast, the presence of mitochondrial disease is relatively common in “2p21 microdeletion syndrome” which involves the deletion of at least four contiguous genes on chromosome 2, SLC3A1, PREPL, PPM1B, and CAMKMT." (PMID 34612606, 2021).
SLC3A1 also shares sentences with these, for which no sentence is quoted: genetic disorder (3 papers); kidney disease (3); brain cancer (2); Dent disease (2); metabolic disease (2); renal tubular acidosis (2); Sepsis (2); adrenocortical cancer (1); Anxiety (1); autosomal dominant tubulointerstitial kidney disease (1); bladder cancer (1); cholestasis (1); collecting duct carcinoma (1); colorectal cancer (1); cystitis (1); diabetic kidney disease (1); dilated cardiomyopathy (1); esophageal cancer (1); Fanconi syndrome (1); FOAR syndrome (1); gallbladder cancer (1); gastric cancer (1); gastroenteropancreatic neuroendocrine tumors (1); Hypercalciuria (1); Hypergonadotropic hypogonadism (1); hypophosphatemic rickets (1); Intellectual disability (1); kidney (1); liver cancer (1); malaria (1).
A further 15 diseases each share a sentence with SLC3A1 in 1 paper.